MIDN (midnolin)
Diseases named in the same sentence as MIDN in open-access papers (continued):
Sharing a sentence is not in itself a finding about the gene and the disease.
cancer (4 papers, 2022 to 2025). A tumor composed of atypical neoplastic, often pleomorphic cells that invade other tissues. "We analysed the immune infiltration in 33 cancers, and the mutation of MIDN is significantly associated with T cells or macrophages." (PMID 40111059, 2025). "Using the Immune checkpoint module of the Sangerbox 3.0 platform, we discovered that MIDN expression was linked with the expression of many immune checkpoint genes in pan-cancer." (PMID 40002690, 2025). "It is suggested that MIDN can be used to predict the prognosis of different cancer types, and its differential expression in human cancers is associated with immune checkpoint genes, which provide evidence for the potential role of MIDN in tumour immunity." (PMID 40111059, 2025). "Comparing the mutation sites of the MIDN gene in 16 cancers, we found that the mutation sites of MIDN varied among different tumours." (PMID 40111059, 2025). "As immune‐related regulators can be promising targets for cancer immunotherapy, we found the association of MIDN with 60 immune checkpoint‐associated genes in cancers." (PMID 40111059, 2025). "Our data were consistent with former GSEA analysis, underlining that MIDN may affect immunity in cancers." (PMID 40111059, 2025). "Notably, the mutation of MIDN in cancers was significantly associated with immune cell infiltration." (PMID 40111059, 2025). "Furthermore, mutations of MIDN in cancers were significantly associated with immune cell infiltration." (PMID 40111059, 2025). "MIDN was mutated in 1.7% of cancers, and deep deletion was the dominant mutation type." (PMID 40002690, 2025). "Targeting midnolin and associated cancer metabolism may be useful in future therapy for HCC." (PMID 35326575, 2022). "According to the UALCAN database, we found a link between MIDN expression and the methylation level of the promoter with a variety of malignancies in different cancers." (PMID 40111059, 2025). "This study presents a robust link between the expression of MIDN and tumour progression across multiple cancer types." (PMID 40111059, 2025). "Immediate‐early genes are the targets of MIDN, and they are also very important in the regulation of cancer." (PMID 40111059, 2025). "The “Pathological Stage Plot” module (GEPIA2) is applied to analyze the correlations between MIDN expression and stages of cancers." (PMID 40002690, 2025). "With the help of the ESTIMATE, TIMER, and CIBERSORT databases, we analysed the immune score, immune cell infiltration, and anti‐cancer immunity cycle depending on the expression of MIDN." (PMID 40111059, 2025). "The correlation of MIDN level with stemness in cancers was also evaluated using the stemness module of the Sangerbox 3.0 platform." (PMID 40002690, 2025). "Then, we evaluated the prognostic value of MIDN mRNA levels in pan-cancer using the Sangerbox 3.0 platform." (PMID 40002690, 2025). "The prognosis value of MIDN expression in pan-cancer is also analyzed using the GEPIA2 and Kaplan–Meier Plotter databases." (PMID 40002690, 2025). "With the help of the TCGA, GTEx, and HPA databases, we revealed that the expression of MIDN was disordered in cancers." (PMID 40111059, 2025). "The relationship between mRNA expression level of MIDN and prognosis in human cancers was analysed using Kaplan–Meier plotter." (PMID 40111059, 2025). "Positive correlations between the expression of YTHDF3, YTHDF2, YTHDF1, and YTHDC1 and MIDN levels were detected in nearly all cancers." (PMID 40002690, 2025). "In cancer, midnolin is needed to adapt to abundant cancer‐related stress, such as oncogene activation, hypoxia, nutrient deprivation, acidosis, high‐demand secretion, metabolite deposition, and endoplasmic reticulum stress." (PMID 38084259, 2023).
cancer (continued). "The regulation of midnolin in cancer and roles of midnolin other than mediating protein degradation would guide the investigations on cancer treatment targeting midnolin." (PMID 38084259, 2023). "MIDN was positively correlated with most immunological checkpoints genes in major cancers." (PMID 40111059, 2025). "Furthermore, we performed the correlation analyses of MIDN levels with stemness, tumor mutational burden (TMB), immune checkpoint genes, immune cell infiltration, and RNA modification genes in cancers." (PMID 40002690, 2025). "The TMB and MSI correlation supports the regulatory role of MIDN in cancers." (PMID 40111059, 2025). "In conclusion, MIDN might represent a potential immunological and prognostic biomarker in cancers as indicated by our comprehensive analysis." (PMID 40111059, 2025). "Furthermore, the expression of MIDN in most cancers was closely related to CD4+ and CD8+ T cells, suggesting its potential regulatory role in tumour immunity." (PMID 40111059, 2025). "Taken together, these findings indicated that elevated levels of MIDN might be a contributor to cell proliferation, epigenomic regulation, and immunity in various cancers." (PMID 40111059, 2025). "Based on these results, we speculated that MIDN may have the potential to predict the response to immunotherapy in the corresponding cancers." (PMID 40111059, 2025). "Nevertheless, the roles of MIDN in cancer are largely unclear." (PMID 40002690, 2025). "Although midnolin has been studied for over two decades, its biological roles, especially in liver and cancer, are largely unknown." (PMID 35326575, 2022). "Whether and how MIDN regulates the EBV-related cancer progression still requires exploration." (PMID 40002690, 2025). "However, the function of MIDN in cancer was rarely reported." (PMID 40111059, 2025). "Moreover, MIDN also contributes to cell proliferation in most cancers." (PMID 40111059, 2025). "Targeting the midnolin‐proteasome pathway might be beneficial for cancer therapy." (PMID 38084259, 2023). "To investigate the function of MIDN in cancers, we used GSEA to analyse MIDN‐related signalling pathway changes in multiple cancers." (PMID 40111059, 2025). "The MIDN level was correlated with several immune checkpoint genes, such as VEGFA, and RNA modification genes such as YTHDF1, YTHDF2, YTHDF3, and YTHDC1 in cancers." (PMID 40002690, 2025). "Using a combination of in vitro/in vivo models and RNA-seq, and identifying midnolin’s significant clinical relevance in HCC, our study is the first to demonstrate a functional role for midnolin in cancer." (PMID 35326575, 2022). "However, the role of MIDN is still not clearly identified in human cancers." (PMID 40111059, 2025).
tumor (4 papers, 2022 to 2025). "Furthermore, we analyzed the correlations between MIDN level and immune cell infiltration, stemness, tumor mutational burden (TMB), RNA modification genes, and immune checkpoint genes." (PMID 40002690, 2025). "A notable correlation between immune cell infiltration and MIDN mutations could also be observed in other tumours." (PMID 40111059, 2025). "After analysing the sequencing results of TCGA via Gene Set Enrichment Analysis (GSEA), results suggested the regulative role of MIDN in cell proliferation and tumour immunity." (PMID 40111059, 2025). "The target genes of FTO determine its promotive or suppressive effects on tumor progression; therefore, how the MIDN/FTO axis affects tumor progression urgently needs to be investigated in the future." (PMID 40002690, 2025). "Prognostic analysis indicates that the expression level of MIDN gains survival benefits or promotes progression in multiple tumours." (PMID 40111059, 2025). "To explore the cell types expressing MIDN in tumour tissues, we analysed the single‐cell expression data of MIDN using 79 datasets from the TISCH database." (PMID 40111059, 2025). "Single cell sequencing results revealed that MIDN is highly expressed in several tumour tissues and also expressed in immune cells." (PMID 40111059, 2025). "As the available numbers of normal tissues were too small compared to those of tumours, we combined the TCGA and GTEx databases to test the different expression pattern of MIDN in normal and tumour tissues." (PMID 40111059, 2025). "We analysed the sCNA of MIDN in various tumours and found amplification in tumours such as ACC, GBM, and SARC." (PMID 40111059, 2025). "In KICH and PAAD tumours, MIDN expression was detected to be lower than that in normal tissues." (PMID 40111059, 2025). "Interestingly, the different prognostic roles of MIDN may be related to the organ microenvironment, and there is a need to explore the different mechanisms of MIDN's action in different tumours for clinical therapy." (PMID 40111059, 2025). "In mechanism, we found that MIDN interacted with the CTNNB1/MMP9 axis, which was verified as an important pathway in suppressing the tumour immune microenvironment." (PMID 40111059, 2025). "The Wilcoxon rank-sum test was used to evaluate expression levels, and we found that MIDN, COMTD1, and RAP2B were highly expressed in tumor tissues and lowly expressed in normal tissues." (PMID 37405477, 2023).
infection (1 paper, 2025). The state of being infected such as from the introduction of a foreign agent such as serum, vaccine, antigenic substance or organism. "Viral titers calculated after infection of Vero cells with supernatant exhibited lower viral titers with MIDN overexpression." (PMID 40439407, 2025).
MIDN also shares sentences with these, for which no sentence is quoted: autism spectrum disorder (1 paper); bladder cancer (1); Cirrhosis (1); colorectal cancer (1); endocervical adenocarcinoma (1); esophageal squamous cell carcinoma (1); eye cancer (1); glioma (1); leukemia (1); melanoma (1); pancreatic cancer (1); peripheral nervous system cancer (1); rectum adenocarcinoma (1); testicular germ cell tumor (1); uveal melanoma (1); vagina cancer (1).